CRP (C-reactive protein)
Diseases named in the same sentence as CRP in open-access papers (continued):
Sharing a sentence is not in itself a finding about the gene and the disease.
cancer (continued). "Patients with cancer reportedly exhibit a stereotypical acute-phase protein response with CRP increasing and albumin falling, which is maintained across different tumor types." (PMID 35807934, 2022). "The modified Glasgow Prognostic Score (mGPS) and “lymphocyte C-reactive protein score” (LCS) are used to assess the inflammation levels in cancer patients." (PMID 35865381, 2022). "Serum levels of cytokines, such as TNFα, IL-1β, IL-6, IL-10, and IL-2R, are increased in SIRS, and among these, IL-6 in particular is known to be involved in cancer progression and C-reactive protein synthesis in the liver." (PMID 35203589, 2022). "The emergence of a systemic inflammatory state in cancer, reflected by elevated CRP levels, is often accompanied by a decrease in serum albumin concentration, sustained weight loss, impaired nutritional status, and increased mortality." (PMID 36585638, 2022). "Fish oil capsules (498 mg EPA and 213 mg DHA) and dietary supplements (100 kcal and 5 g protein) were administered for 8 weeks to 20 patients with cancer and inflammation [C-reactive protein (CRP) ≥0.30 mg/dl]." (PMID 35949598, 2022). "Unique pathophysiological changes are still under examination, but several studies have shown that prognostic biomarkers, such as CRP, D-dimer, prothrombin time, and serum IL-6 levels, were significantly higher in cancer patients than in non-cancer patients." (PMID 35466178, 2022). "The increase in serum CRP level in patients with cancer is correlated with the proliferation of tumor cells and production of inflammatory cells and related inflammatory factors." (PMID 36684183, 2022). "Women with high CRP had significantly higher overall and cancer-specific mortality rates than those with low CRP in both univariable and multivariable analyses." (PMID 34802721, 2022). "In Cox regression univariate analysis high SIII, high CRP, positive lymph node status, R1 margin status, higher T stage, high tumor differentiation, high ASA-score, and high CA19-9 were associated with cancer-specific survival." (PMID 35296013, 2022). "Increased concentrations of inflammatory markers such as C-reactive protein (CRP) and interleukin (IL-6) during cancer treatment were related to the development of feelings of fatigue." (PMID 35800955, 2022). "Previous physical activity interventions showed beneficial changes in biomarkers implicated in these pathways, including insulin, leptin, IGFs, and C-reactive protein (CRP) in cancer survivors." (PMID 36099282, 2022). "Since CRP is produced by the liver as part of the acute phase response, its levels correlate with cancer progression." (PMID 35965580, 2022). "Although we observed three non-linear association patterns between CRP concentration and site-specific cancers, the inflection points were at 3mg/L of CRP concentration, and at 1mg/L after log-transformed, consistently." (PMID 36117174, 2022). "Amidst 180 eligible patients with raised PLT, ALP and CRP, 54 cancers were detected, giving a PPV of 30.0%." (PMID 35482741, 2022). "Rehabilitation program for deafferents types of cancer after anticancer therapy revealed significant improvements in CRP level, QOL, and fatigue." (PMID 35935260, 2022). "The NLR has been suggested to be a useful marker to measure subclinical inflammation in humans, and it has been proven to correlate well with established inflammatory markers, such as the CRP, and has prognostic value in patients with malignancies." (PMID 35056629, 2022). "Few studies focused on older persons, except a cohort study including 2400 American septuagenarians that found associations between higher CRP, IL-6 and TNF with all cancer incidence." (PMID 35406394, 2022). "Among cancer patients, CRP also plays a role as a prognostic marker in ovarian, oesophageal, and gastric cancer." (PMID 36010631, 2022). "In our study we show that Leukocytes, Neutrophils, NLR, LDH and CRP are significantly higher in cancer patients who were referred late to a SPCC." (PMID 36503625, 2022).
cancer (continued). "We found that MMP-8 immunoexpression in cancer cells combined with a low plasma CRP level (<10 mg/L) is a strong predictor of a favourable outcome in PDAC, whereas no MMP-8 expression and an elevated CRP level (≥10 mg/L) predicts a poor prognosis." (PMID 35328734, 2022). "Vitamin B6 levels decrease with increasing levels of inflammatory markers such as interleukin-6, C-reactive protein, and the alpha tumor necrosis factor which are involved in cancer." (PMID 35399658, 2022). "In particular, the prediction accuracy of random forest was >90%, and decision tree highlighted disease duration, NLR, and CRP as critical clinical parameters for recognizing cancer patients." (PMID 35237262, 2022). "In human medicine, several studies have recently shown the prognostic potential of the CRP/ALB ratio as a prognostic factor in cancer patients with different types of solid tumors." (PMID 35873678, 2022). "Many studies have shown that CRP is an independent biomarker for predicting prognostic outcomes in various cancers." (PMID 36072935, 2022). "Further multivariate analysis presented that BMI < 25.0 kg/m2 (HR = 3.516, 95% CI = 1.076–11.492, P = 0.037) remained independent prognostic factors after adjusting age, CRP, cancer stage, and lesion locations." (PMID 35773692, 2022). "Considered to be the most practical, cost‐effective and robust biomarker of cancer cachexia, C‐reactive protein (CRP) is used to assess prognosis and predict quality of life in cancer cachexia patients." (PMID 36251564, 2022). "After additional adjustment for potential confounders (age, gender, BMI, smoking, lesion locations, cancer histological type and stage, PT, APTT, triglycerides, HDL-C, WBC, platelets, and CRP), the strength of this association remained significant." (PMID 34991557, 2022). "Future studies focusing on the performance of CRP/Albumin ratio in predicting overall survival in Chinese cancer patients are warranted." (PMID 36501196, 2022). "Regarding cancer, our findings for CRP and HbA1C are also quite in line with those from previous prospective studies." (PMID 34935094, 2022). "CRP is an acute protein involved in systemic inflammation, which can be also used as an indicator to predict survival in patients with cancer." (PMID 36096761, 2022). "As a systemic inflammatory mediator, CRP is an evolutionarily conserved innate immune polymer protein, which has been considered as an important biomarker to predict cancer patient survival." (PMID 36266627, 2022). "Although the C-reactive protein to albumin ratio (CAR) has been repeatedly reported to be related to poor prognosis in various cancers, including pancreatic, gastric, lung, and esophageal cancer, its role in TETs remains to be elucidated." (PMID 36397047, 2022). "Regarding endurance exercise, patients with different cancer types had a 6% reduction in CRP levels after 12 weeks (3 week−1) of HIIET, but this was significantly different to the LICET group who exhibited a 19% increase." (PMID 35088134, 2022). "The score system of Glasgow prognostic score (GPS) based on ALB and CRP was also confirmed as one of the most widely recognized scores for predicting clinical outcomes in a variety of cancers." (PMID 35300627, 2022). "CRP is a marker of systemic inflammation and has been used to determine the prognosis and predict the clinical results of cancer patients." (PMID 36362488, 2022). "The increased production of acute phase proteins by liver contributes to inflammation in patients with cancer and the C-reactive protein (CRP) appears to be an important parameter for prognosis." (PMID 36158184, 2022). "In this context, it is noteworthy that circulating levels of the acute phase reactant, C-reactive protein (CRP), have been found to be moderately elevated in patients with various types of cancer." (PMID 35223501, 2022).
cancer (continued). "This determinant of T cell function predicts that the presence of pro-inflammatory mediators, including IL-6, CRP, and other factors, inhibits T cell effector function and culminates in poor clinical outcomes in many cancers." (PMID 35359426, 2022). "The improvement in the immunity observed in blood samples of the patients doing exercise at home revealed a significant reduction in TNF-α, CRP, IL-8, and an increase in NK cell levels which ultimately give advantages to the cancer patients." (PMID 35935260, 2022). "The calculation equation as follow: Y (total score) = Age score + Gender score + Cancer score + T-SPOT score + CRP score + ADA score." (PMID 36056429, 2022). "The combination of elevated CRP (>10 mg/L) and decreased albumin (<35 g/L) corresponds to higher mGPS, which correlates with systemic inflammation and poor outcome of cancer therapy." (PMID 36232415, 2022). "In this study, we developed the clinical model (model 1) with independent clinical predictors of age, elevation of C-reactive protein level, fever and family history of cancer, with an AUC of 0.786 and an accuracy of 69.79%." (PMID 36461012, 2022). "Among them, IL-6, TNF-α, IL-1β, CRP, and albumin are the most investigated, but the correlation between them and cancer cachexia is elusive in humans." (PMID 36158184, 2022). "The modified Glasgow prognostic score (mGPS), which incorporates both serum CRP (cutoff: 10 mg/L) and albumin (cutoff: 35 g/L) levels, is an independent overall survival (OS) and cancer-specific survival predictor in OSCC." (PMID 35242712, 2022). "Cancer patients showed increased CRP levels, indicative of inflammation, and the level of CRP correlated with the amount of NETs in plasma." (PMID 35309730, 2022). "As such, while other studies have found that IL-6, IL-1b, and CRP is significantly up-regulated in specific groups of cancer patients exhibiting poor sleep, this/these biomarker(s) did not correlate significantly with sleep quality in our broader cohort." (PMID 36213755, 2022). "The predicted probability formula of model 5 was as follows: P(z) = 1/(1 + e−z), z = 0.033 × age—0.686 × elevation of C-reactive protein level—1.995 × fever + 0.797 × family history of cancer + 1.459 × air space—0.212 × CT attenuation value." (PMID 36461012, 2022). "Although systemic inflammation is not considered in the current classification as a parameter for diagnosing cancer cachexia, several authors have considered the measurement of inflammatory markers, such as CRP and IL-6, at the blood level." (PMID 36072935, 2022). "The amount of IL-6 in the circulating blood reflects the cancer state and when IL-6 is elevated, CRP is increased and albumin is decreased." (PMID 36260237, 2022). "It was found that the levels of D-dimer, FDP, CRP and IL-6 in cancer patients were significantly higher than those in the COVID-19 cohort." (PMID 36439504, 2022). "The inflammation-based prognostic score LCS combining CRP and lymphocyte count was originally used to measure systemic inflammatory status and predict prognosis in cancer patients." (PMID 35865381, 2022). "Results have demonstrated that the group's mean of NLR, PLR, and CRP levels with malignant tumors was significantly (P<0.001) higher than patients with benign masses." (PMID 36532648, 2022). "It is recognized that ongoing systemic inflammatory responses (indicated by an elevated CRP) in cancer patients can lead to poor survival due to reasons such as increased protein breakdown." (PMID 35619963, 2022). "An elevated serum CRP level has also been demonstrated to be an independent prognostic factor in patients with various types of cancers." (PMID 34980029, 2022). "Subgroup analysis of CRP in patients with cancer showed that CRP levels and surgery status (P interaction=0.005) and TNM stage (P interaction= 0.031) had significant interactions." (PMID 35752767, 2022).
cancer (continued). "For all cancer sites, cases were more likely to have BMI≥30 kg/m2, and higher median values for leptin, CRP, and fasting insulin relative to controls." (PMID 35048536, 2022). "Intriguingly, relative hematopoietic changes, such as neutrophil: lymphocyte ratio (NLR), platelet: lymphocyte ratio (PLR), and inflammatory response CRP levels alteration, have recently been recognized as poor prognostic indicators in various cancers." (PMID 36532648, 2022). "Recently, some studies have shown that postoperative systemic inflammation is significantly correlated with the postoperative prognosis of cancer patients through evaluating serum CRP level." (PMID 35719680, 2022). "The ROC was used to choose the most appropriate cut-off for the NLR, PLR, and CRP levels to distinguish patients with benign mass from malignant tumors." (PMID 36532648, 2022). "By influencing C-reactive protein, tamoxifen kills cancer cells or inhibits their growth or increases the levels of nuclear factor erythroid 2-related factor 2 (Nrf2) to cause cell oxidative stress." (PMID 35057070, 2022). "In diabetic patients, serum 25(OH)D, cadmium, and CRP were related to all-cause mortality; serum 25(OH)D was related to cardiovascular mortality; CRP was related to cancer mortality." (PMID 35571939, 2022). "CRP was investigated with the possibility of refining the at-risk group and increasing the PPV for cancer detection." (PMID 35482741, 2022). "Elevated CRP is a marker of systemic inflammation and is considered a predictor of poor survival in patients with various cancers." (PMID 34956932, 2021). "Since CRP apparently potentiates IgG-mediated destruction of several types of target cells, its application in immunotherapies (cancer and infectious diseases) can be envisioned." (PMID 33790888, 2021). "So, the correlation between prognostic factors and severity of the cancer as measured by CRP has remained uncertain." (PMID 34926085, 2021). "While 2408 fewer people with unexpected WL would be referred unnecessarily per 100,000 people tested, using an mGPS = 2 compared to a raised CRP, 125 fewer people with cancer would be referred for investigation." (PMID 33558706, 2021). "Our current study shows that, for the specific group of older cancer patients in need of oncologic surgery, an elevated plasma level of preoperative CRP of only ≥10 mg/L is an unfavorable independent prognostic factor for overall survival after surgery." (PMID 33920422, 2021). "The present results indicate that significant and direct relationships exist between CRP levels and pain in patients with advanced cancer cachexia." (PMID 34223511, 2021). "Concentrations of CCR3, CEA, and CRP in the total cancer group were statistically significantly higher when compared to the control group (in all cases p < 0.05)." (PMID 34204490, 2021). "Serum YKL-40, IL6, and CRP were found to be elevated in advanced-stage cancer patients with poor performance statuses." (PMID 34579512, 2021). "Considering the existing literature, CRP appears to constitute biomarker of growing importance for metastatic stages and survival in cancer patients." (PMID 33562331, 2021). "There exist different inflammatory markers among malignant tumours and the most common used by oncologists are C-reactive protein (CRP), Glasgow Prognostic Score (GPS) and platelet-to-lymphocyte ratio (PLR)." (PMID 34429466, 2021). "In the present study, increased NLR was correlated with elevated CRP and D-dimer levels among cancer patients." (PMID 33928250, 2021). "Parameters at D0 associated with mortality in our cohort (age, sex, history of CKD, active cancer, lower eGFR and platelet counts, and higher CRP) have already been reported by others." (PMID 33484426, 2021). "Inflammation scores based on general inflammation markers as leucocyte count or C-reactive protein have been evaluated as prognostic markers of inferior survival in several cancers." (PMID 33509254, 2021).
cancer (continued). "Hs-CRP was significantly elevated in the early stage in comparison to the late stage among cancer patients, meanwhile Apo-B behaved inversely." (PMID 34711013, 2021). "Materials and methods: A total of 74 cancer patients were evaluated for presepsin, lactic acid, C-reactive protein (CRP) levels, and white blood cell count (WBC)." (PMID 34065685, 2021). "Previous studies have shown that CRP/Alb ratio is a promising prognostic biomarker for critically illness, cancers, and Kawasaki disease." (PMID 34900028, 2021). "Several in vitro and in vivo studies investigating a possible role for CRP as an agent that can affect cancer disease have appeared in the literature." (PMID 34552600, 2021). "Several inflammatory markers, for instance, C-reactive protein (CRP), leukocytes, neutrophils, lymphocytes, monocytes, macrophages, and platelet counts are associated with various cancer types." (PMID 34869556, 2021). "Most cancer patients had increased level of C-reactive protein (CRP); less frequent were increased levels of aspartate aminotransferase (AST), alanine aminotransferase (ALT), D-dimer." (PMID 33735106, 2021). "CRP has also demonstrated a correlation with cancer-specific survival (CSS), and freedom from PSA failure in metastatic castration-resistant prostate cancer prior to abiraterone and enzalutamide." (PMID 34926085, 2021). "The B12/CRP index (BCI) was first intended as a prognosis tool to predict 90-day mortality after advanced cancer diagnosis." (PMID 35008333, 2021). "Elevated levels of CRP have been reported as a prognostic factor for poor survival outcomes in a variety of cancers." (PMID 33406501, 2021). "GPS is a cumulative inflammation-based cancer prognostic marker based on elevated serum CRP and decreased albumin concentration." (PMID 34677378, 2021). "High levels of CRP have a profound suppressive effect on adaptive immunity in cancer patients, leading to a chronic state of immune suppression and ultimately to tumor initiation and progression." (PMID 34926263, 2021). "We must note that only one NAT patient with CRP ≥ 3 mg/l survived for more than 5 years, thereby emphasizing the role of inflammation in cancer survival." (PMID 33437015, 2021). "Some studies have shown the usefulness of measuring the vitamin B12/CRP index (B12 vitamin × CRP) (known as BCI) in the management of older cancer patients." (PMID 35008333, 2021). "Several previous studies have found that the level of CRP negatively correlates with both OS and cancer-specific survival." (PMID 34211459, 2021). "GPS is also useful for advanced cancer patients in palliative care (palliative care unit, palliative care team in general wards, home palliative care), and 71% of the patients had CRP ≥1.0 mg/dL and albumin <3.5 g/dL (=GPS 2)." (PMID 33808957, 2021). "We also found that the CRP concentration in CRC patients was 16.8-fold higher compared to non-cancer individuals." (PMID 34441316, 2021). "C-reactive protein (CRP), an acute-phase reactive protein produced by hepatocytes, is generally used for the assessment of inflammation, including cancer-associated inflammation." (PMID 34441316, 2021). "With the progress of research on the relationship between tumor and inflammation, many studies on CRP or CRP-based inflammatory markers as predictors of various cancers have been reported, including urologic tumors." (PMID 34926263, 2021). "CRP has been reported to be both, prognostic of outcome and predictive of response to chemotherapy, in a range of cancers." (PMID 34884980, 2021). "Among this variables, age, cancer, C-reactive protein, moderate/high disease activity, LV mass and E/E′ ratio (parameter of LV diastolic function) were included in the multivariate logistic regression model." (PMID 33083946, 2021). "As with other cancer sites, these results can be unconvincing based on the timing and methodology of CRP level collection." (PMID 34926085, 2021).